IL13 (interleukin 13)
Diseases named in the same sentence as IL13 in open-access papers (continued):
Sharing a sentence is not in itself a finding about the gene and the disease.
tumor (continued). "DTIC suppressed more efficiently pro‐inflammatory cytokines (IL‐17A, IL‐8) and immune‐modulatory cytokines (INF‐α2, IL‐13) that promote tumor growth or immune evasion." (PMID 39475010, 2024). "IL-25 production is stimulated by IL-4 and IL-13 cytokines—produced by tumor cells and Th2 cells—and periostin produced by dermal fibroblasts." (PMID 38607023, 2024). "The pleiotropic nature of IL-13 signaling encompasses muscle metabolism and metastatic tumor burden." (PMID 39272892, 2024). "Both SIA‐CIgG CAR‐T cells and HER2 CAR‐T cells secreted more IL‐2, IL‐5, TNF‐α, IFN‐γ, and IL‐13 compared to non‐transduced T cells when eliminating tumor cells." (PMID 39178136, 2024). "Anti-tumor macrophages (M1) can polarize into pro-tumor macrophages (M2) via IL-4, IL-10, and IL-13." (PMID 39125923, 2024). "This shift will increase the immunosuppressive cytokines (IL-2, IL-4, IL-7, IL-13, and IL-15) production by neoplastic elements which lead to tumor growth and spread." (PMID 38850434, 2024). "M2 stimulates tumor growth and invasion through the secretion of IL-4, IL-13, IL-10, vitamin D3, and glucocorticoids." (PMID 39201801, 2024). "IL-4, IL-5, and IL-13, which are related to the Th2 immune response, can create an immunosuppressive environment that favors tumor growth." (PMID 39456897, 2024). "IL-13 enhances the activity of tumor-specific cytotoxic T-lymphocytes (CTLs) and promotes their disruptive effect on tumor cells." (PMID 39267832, 2024). "Following differentiation, Th2 cells secrete IL-4, IL-5, IL-10, IL-13, and IL-17 and eventually undergo tumor growth and metastasis." (PMID 38238581, 2024). "The OC has a tumour microenvironment that is immunosuppressive and has high levels of cytokines like IL-4 and IL-13 that promote the recruitment of immunosuppressive cells." (PMID 38974022, 2024). "Cytokines such as IL-4 and IL-13 within the tumor microenvironment regulate the polarization of tumor-associated macrophages (TAMs) through downstream Stat6-dependent inhibition of Arg1, activation of PPARγ, and TSC1-mediated inhibition of mTOR." (PMID 39676873, 2024). "IL-25 enhanced IL-13 production from tumor cells via STAT6 signaling pathways, resulting in the augmentation of a Th2-dominant microenvironment." (PMID 38607023, 2024). "In contrast, M2 macrophages, activated by IL-4 and IL-13, contribute significantly to tumor growth, metastasis, and immune evasion." (PMID 39766056, 2024). "M2-like macrophages mediate the immune escape of tumor cells through PD-1 and are activated by interleukin (IL)-4, IL-10, IL-13, or colony-stimulating factor 1 (CSF-)." (PMID 39113885, 2024). "This indicates the antagonistic activity of the mutual direct relationship between tumor cells and monocytes in relation to the release of IL-13." (PMID 39057050, 2024). "In our studies, we demonstrated a relatively high level of released IL-13 in both mono- and co-cultures of tumor cells/macrophages." (PMID 39057050, 2024). "In contrast, interleukins like IL-4, IL-5, IL-10, and IL-13, which contribute to the chronic inflammatory protumorigenic response, promote tumor progression and immune evasion through their interactions with the tumor microenvironment." (PMID 39456897, 2024). "IL-13 and IL-18 play complex and diverse roles in the development of cancer, involving not only tumor growth, dissemination, and immune evasion mechanisms but also providing new targets for cancer prognostic biomarkers and therapeutic interventions." (PMID 39267832, 2024). "Cytokines secreted by Th2 cells, such as IL-4 and IL-13, disrupt the balance between Th1 and Th2, shifting the immune response from Th1 to Th2, thereby promoting tumor growth." (PMID 39867914, 2024). "Both TGF-β and the combined profile of IL-4/IL-13 signaling pathways were found to be consistently upregulated across almost all tumor types." (PMID 39035007, 2024). "Remarkably, Il13 is also a cancer immunosurveillance factor then presented in tumor microenvironment." (PMID 39594640, 2024).
tumor (continued). "The other activated macrophage phenotype, M2-like TAMs, are switched on by Th2 cells cytokines such as IL-13, IL-10 and IL-4, leading to tumor progression, inducing angiogenesis and metastasis, and inhibiting the anti-tumor response." (PMID 39050852, 2024). "Research shows that basophils infiltrate various human cancers and induce immune protection in the tumor microenvironment by secreting cytokines such as IL-4/IL-13 to polarize macrophages to the M2 phenotype." (PMID 38388357, 2024). "Overall, IL-13 is heavily involved in the initiation of a type-2 immunity, whose role in anti-tumor immunity is currently being examined." (PMID 39411143, 2024). "Numerous studies have highlighted that IL-13 and IL-4 have a synergistic effect, and their expression promotes tumor cell growth and proliferation in CTCLs." (PMID 38607023, 2024). "Earlier studies reported an essential role of MCs for PDAC tumorigenesis, which was mainly attributed to MC-released IL13 supporting tumor cell proliferation, and myc-dependent promotion of angiogenesis." (PMID 38942797, 2024). "The recruitment of eosinophils into the oral tumour site is mediated by inflammatory cytokines and chemokines, primarily attributed to IL-4 and IL-13, which are secreted from T helper cells (Th2)." (PMID 38673958, 2024). "As Th2 cytokines, IL4 and IL13 have been reported to restrain the immune response to tumor cells and promote the proliferation of KRAS-mutant cells." (PMID 36975441, 2023). "Interleukin-13 (IL-13) is a cytokine that plays a significant role in negatively regulating anti-tumor immunity." (PMID 38067251, 2023). "Antibodies neutralizing TSLP or OX40L inhibited IL-13 production and tumor growth in a xenograft model." (PMID 37835465, 2023). "In contrast, IL-13 inhibitor has been observed to be a pivot in the enhancement of antitumor immunity in some tumor models." (PMID 37152373, 2023). "Taken together, our results reveal that the transcription factor SHN3 is a key mediator of the tumor-promoting IL-13/IL13Rα2/PTP1B signaling pathway." (PMID 37963919, 2023). "Th2 cells are a crucial component of type II immune responses by secreting a wide spectrum of cytokines such as IL-4, IL-5, IL-9 and IL-13, which affect both tumor cells and several types of immune cells." (PMID 36376448, 2023). "β2AR signaling can also polarize macrophages from M1 to M2 type, thereby enhancing anti-inflammatory cytokines like IL-10, IL-4 & IL-13, and decreasing pro-inflammatory cytokines like INFγ, TNFα, IL1β, CCL2, CCL3 and CCL4 to cause tumor progression." (PMID 37006295, 2023). "We next examined two master regulatory factors associated with M1-M2 macrophages’ switch, G-CSF and IL-13 in the serum derived from MDX mice and tumor-bearing MDX mice." (PMID 37628775, 2023). "Variant 2, which lacks the downstream signaling pathway, is restricted to tumor cells (except for the testis), and acts as a decoy receptor that competitively sequesters IL-13, preventing apoptosis of tumor cells and driving tumor progression." (PMID 36900205, 2023). "IL13 is involved in the maintenance of cellular stemness, and our previous study demonstrated that IL13 promotes tumor stemness." (PMID 37534250, 2023). "At low antigen density, IL13-28ζ CAR T cells demonstrated more rapid and efficient tumor killing than IL13-BBζ CAR T cells." (PMID 36968221, 2023). "TAMs have M1 macrophage characteristics, and M1 TAMs exhibit high amounts of pro-inflammatory factors (e.g. TNF-α) and anti-tumour factors IL-12, IL-13, IL-1, and TNF-β, which can boost Th1 responses and tumour-killing capability." (PMID 37304305, 2023). "Between the second-generation CAR T cell variants, IL13-BBζ again outperformed IL13-28ζ CAR T cells, with more efficient tumor elimination and CAR T cell proliferation following repetitive tumor addition." (PMID 36968221, 2023).
tumor (continued). "Among macrophages, M2 macrophages usually play an antiinflammatory role in the tumor microenvironment, with poor antigen presentation ability, low IL-12, and high IL-10, IL-4, and IL-13 secretion characteristics, as well as immunosuppressive effects." (PMID 38813495, 2023). "M2 macrophages, on the other hand, activated by IL-4, IL-10, and IL-13, promote tumor growth and suppress anti-tumor immune responses." (PMID 38201551, 2023). "Along these lines, Geskin and colleagues previously documented the importance of the synergistic effect of the Th2-type cytokines IL-13 and IL-4 in promoting tumor cell growth and proliferation in CTCL." (PMID 37190290, 2023). "In this context, the levels of GM‐CSF, TNF‐α, IFN‐γ, IL‐1β, IL‐2, IL‐4, IL‐6, IL‐10, and IL‐13 in the peripheral blood of H22 tumor‐bearing mice were detected." (PMID 36043445, 2023). "In this regard, Th2 cells facilitate tumor growth by producing pro-tumor factors such as IL-4, IL-5 and IL-13." (PMID 37773521, 2023). "While the resulting tuft cell - ILC2 feed-forward circuit promotes gastric metaplasia and tumor formation, genetic depletion of tuft cells or ILC2s, or therapeutic targeting of IL13 or IL25 alleviates these pathologies in mice." (PMID 37898600, 2023). "The IL-33-mediated optimal immunometabolic reprogramming in ILC2s also requires ROS, and its inhibition can prevent its tumor-promoting role by suppressing IL-5 and IL-13 release." (PMID 37275901, 2023). "Th2 cells have been reported to promote tumor progression by releasing inflammatory factors such as IL-4/IL-13, and by promoting M2 macrophage polarization and activation of myeloid-derived suppressor cells (MDSCs)." (PMID 37744268, 2023). "Recent studies show that increased IL-33 expression in colon cancer cells promotes PPARγ expression in ILC2s, leading to IL-13 release and facilitating tumor migration." (PMID 37686309, 2023). "We found that a significant gradient toward the serum (CXCL9, IL6, IL10, IL13) or the tumor tissue (IL1B) exists for all cytokines in question." (PMID 36980700, 2023). "IL-33 activates tumor-associated macrophages and dendritic cells by binding to its receptor, ST2, triggering the release of abundant Th2 cytokines, including IL-10, IL-4, and IL-13, which inhibit immune cell responses, hampering tumor clearance and control." (PMID 37686309, 2023). "The primary tumor also contains tumor-associated macrophages (TAM) that promote a “pro-tumor” environment by producing anti-inflammatory cytokines such as IL-10 and TGF-beta via the stimulation of IL-13 and IL-4." (PMID 36769180, 2023). "Among the cytokines belonging to the panel identified, only IL-13 seems to harbor exclusively pro-tumor effects." (PMID 36851213, 2023). "Given that IL-13 is expected to support the maintenance of MDCSs, a trial combining IL-13 blockade with oral administration of WTMCGEP for promoting effective tumor eradication in immunocompetent hosts should be considered." (PMID 37152373, 2023). "On the other hand, contrasting evidence suggests that IL-13 can also promote tumor growth by inhibiting the activity of cytotoxic lymphocytes and inhibiting the release of IFN-γ." (PMID 36980536, 2023). "Significantly higher levels of both G-CSF and IL-13 were observed in the serum of tumor-bearing MDX mice as compared to MDX mice." (PMID 37628775, 2023). "High‐level expression of this receptor in tumor cells would result in a situation in which the anti‐tumor activity of IL‐13 is compromised, leading to the nullification of cellular immunity and the occurrence of tumor escape." (PMID 36806727, 2023). "The authors found out that, due to iNOS activity, the classic Th2 response was completely (IL‐4 and IL-13) or markedly (IL‐5, IL‐6, IL‐9, and IL-10) inhibited after tumor irradiation." (PMID 37347290, 2023).
tumor (continued). "Even though there has been little research into how ILC2s influence tumorigenesis and/or progression, ILC2s and/or their signature cytokines, such as IL-5 and IL-13, have been shown to be involved in pro- and anti-tumor immune responses." (PMID 37896962, 2023). "To conclude, tumor-released factors along with IL-4/IL-13-mediated cell signaling pathways provide M2a macrophages with the ability to promote tumor progression." (PMID 37108657, 2023). "Accordingly, if taking advantage of IL-13 derived from mature NK cells for reducing tumor radioresistance, the ability of IL-13 to promote groups of protumor immune cells must be considered." (PMID 38264648, 2023). "TAMs are typically M2-like and polarized by immunosuppressive cytokines such as IL-4, IL-13, or IL-10 in the tumor microenvironment." (PMID 37175092, 2023). "On the other hand, M2 macrophages induced by IL-4 and IL-13 play a key role in tumor progression and metastasis." (PMID 36693070, 2023). "More specifically, it was reported that IL-13 is produced by malignant lymphoma cells and acts as an autocrine factor regulating tumor cell proliferation through IL-13R signaling in both CTCL skin lesions and SCs in blood." (PMID 37190290, 2023). "Th2 cells play a pro-tumorigenic role by secreting IL-4, IL-5, and IL-13, which promote tumor growth and metastasis." (PMID 37324186, 2023). "On the other hand, M2-polarized macrophages, driven by M-CSF, TGF-B, IL-4, IL-10 and IL-13, are believed to promote wound healing, angiogenesis and tumor growth by producing tumor growth factor (TGF)-β, IL-10, CCL17, CCL18, CCL22, CD206, CD204 and CD163." (PMID 37372147, 2023). "Nevertheless, given their overarching effects on tumour immunity, acting upstream of the main effector type 2 cytokines IL-4, IL-5, IL-9, and IL-13 and T cells, the prospect of therapeutically targeting these cytokines is promising." (PMID 37455828, 2023). "Macrophages M1 induced by interferon-gamma and LPS can kill tumour cells and pathogens, whereas macrophages M2 induced by IL-4, IL-10, and IL-13 exhibit anti-inflammatory activity and contribute to tumour invasion and angiogenesis." (PMID 37370746, 2023). "In conclusion, we have uncovered the participation of SNH3 in the IL-13/IL13Rα2/PTP1B pathway to promote tumor growth and invasion." (PMID 37963919, 2023). "This combined treatment notably elevated CD4+ T-cell presence within the tumor microenvironment and increased IL-5 and IL-13 tumor levels, while simultaneously decreasing CD38 in the tumor stroma." (PMID 37689790, 2023). "HT29 cells have been shown to express WT PTEN: a tumor suppressor that negatively regulates IL-13-dependent PI3K/AKT (PKB) signaling." (PMID 36835075, 2023). "Results showed that liposomes functionalized with IL-13 displayed an increased ability to release DOX in the tumor site and exerted an improved therapeutic effect compared with unfunctionalized liposomes." (PMID 36986798, 2023). "These cells can be converted into TAMs through soluble factors present in the tumor microenvironment such as IL-6, interleukin-10 (IL-10), interleukin-4 (IL-4), interleukin-13 (IL-13) and TGF-β57-60." (PMID 37215442, 2023). "Consistent with the expression of Il13ra1 and Il17rb on tuft cells, IL25 or IL13 stimulation of tumor organoids increased their size, while treatment of organoids with an α-IL25 neutralizing antibody resulted in reduced organoid growth." (PMID 37898600, 2023). "Inhibiting IL-13 has many theoretical benefits, including reducing MDSCs and M2 TAMs, while promoting anti-tumour IFNγ+ and T cell infiltration." (PMID 37455828, 2023). "In contrast, M2 macrophages that are activated by IL-13 and IL-4 are often employed as accelerators of tumor progression." (PMID 37346073, 2023). "To investigate the influence of IL13Rα1 expression in healthy tissue on the trafficking of IL13-variant CAR T cells, we conducted in vivo biodistribution studies in a bilateral tumor model." (PMID 35939683, 2022).
tumor (continued). "Macrophages are a heterogenous population of terminally differentiated monocytes that range in their function from pro-inflammatory and anti-tumor (M1 phenotype) to pro-tumor tissue remodeling (M2 phenotype), induced by IL-4, IL-10, IL-13, and CSF-1." (PMID 36223740, 2022). "Cytokines produced by Th2, particularly IL-4 and IL-13, can not only reduce anti-tumor immune responses, but also can directly accelerate tumor growth induced by KRAS transformed cells." (PMID 36408139, 2022). "Anti-IL-25R treatment significantly reduced tumor number and size, and decreased IL-4 and IL-13 expressing tumor ILC2s." (PMID 35658010, 2022). "IL-13 is produced by NK cells which prevent metastases or to kill tumour cells in the circulation before reaching the liver in in vivo UM models." (PMID 36698840, 2022). "While type “M2” is induced by Interleukin-4 (IL-4) or Interleukin-13 (IL-13), and has a tumor-promoting effect." (PMID 36741415, 2022). "The conditioned medium of IL-13-treated M2 macrophages induces tumor invasion, migration, and angiogenesis of A549 and H1299 cells." (PMID 35600336, 2022). "M-CSF can recruit monocytes to the tumor tissue where IL-4, IL-10, IL-13 and other factors present in the tumor microenvironment can induce the differentiation of monocytes into TAMs." (PMID 35741108, 2022). "CD56dimCD16+ NK cells clear tumor cells through cytotoxic activity, and CD56brightCD10−/low NK cells can suppress immune reaction by secreting IL-13." (PMID 36293435, 2022). "ILC2s can suppress immune response against tumor through IL-13-mediated enhancement of MDSCs expansion, alternatively they favor anti-tumor immunity through IL-5-mediated cooperation with DCs." (PMID 36578079, 2022). "For example, Dong and colleagues described that fenretinide (4-HPR) significantly suppressed IL-4/IL-13 induced M2 polarization, resulting in fewer M2 macrophages in tumor tissues and dramatically decreased tumorigenesis." (PMID 35193986, 2022). "The tumor cells in the lesional skin of the tumor-stage shift to a Th2 phenotype, which is characterized by the production of IL-4, IL-5, IL-10, and IL-13." (PMID 36295105, 2022). "In contrast, the M2 phenotype is related to the immunosuppression in the tumor microenvironment by generating cytokines such as IL-4 and IL-13 and establishing a permissive environment for tumor progression." (PMID 35317079, 2022). "The exogeneous FA consumption and de novo FA synthesis contributed to the cancer stemness of the isolated HCC clones, whereas the cytokine receptor signaling, including receptors for IL-4 and IL-13, enhanced tumor growth." (PMID 35721518, 2022). "M2 tumor-associated macrophages (TAMs) are stimulated by anti-inflammatory cytokines (IL4 and IL13) and enhance the tumor growth by down-regulation of the inflammatory response." (PMID 35736195, 2022). "Usually, M2 or alternatively activated macrophages are activated by IL-4, IL-10, IL-13, and glucocorticoid hormones, express high levels of IL-10 and low levels of IL-12, and facilitate tumor progression." (PMID 35928634, 2022). "IL-13 can also bind to IL-13Rα2 on tumor cells and enhance tumor invasion and metastasis through activating ERK/activator protein 1 (AP-1) signaling and matrix metalloproteinases." (PMID 35721518, 2022). "IL-13 is an inflammatory factor that has multiple functions including regulation of tumor development." (PMID 35600336, 2022). "Once in the TME, macrophage polarization can be driven by tumor cells, as well as by “tumor-educated” immune cells releasing M2-skewing factors such as IL-4, IL-13, immunocomplexes, transforming growth factor-β (TGF-β) or M-CSF." (PMID 36359283, 2022). "IL-4, which shares its pathway with IL-13, is known to induce Lyve-1 and other LEC markers in tumor-recruited CD11b+ cells, whereas deficiency in IL-10 receptor (IL-10R) caused impaired lymphatic formation due to decreased generation of M2 macrophages." (PMID 35442077, 2022).